TNF (tumor necrosis factor)
Diseases named in the same sentence as TNF in open-access papers (continued):
Sharing a sentence is not in itself a finding about the gene and the disease.
malaria (continued). "Both malaria and dengue have been associated with a strong activation of acute phase response (IL-6, TNF-α, and IL1-β) and Th1 cytokines (IFN-γ and IL-12)." (PMID 27128316, 2016). "The associations between TNF allele variants and malaria rates were generally more pronounced in the analysis of all episodes than in the analysis of first episodes." (PMID 26088606, 2015). "Malaria mortality is associated with exaggerated host responses to inflammatory factors such as interferon gamma (IFNγ), tumor necrosis factor alpha (TNFα), free heme, C-X-C motif chemokine 10 (CXCL10) and parasite-derived cytotoxins." (PMID 26555697, 2015). "For this reason, the analysis of all episodes reflects with more validity associations between TNF allele variants and malaria rates than analysis of first episodes." (PMID 26088606, 2015). "As a consequence, for studies that recruited controls from a hospital setting, the strength of the association between TNF allele variants and malaria will be underestimated if these controls suffered from a condition that is associated with TNF genotype." (PMID 26088606, 2015). "This is plausible, because TNF genotypes have also been associated with a variety of disorders other than malaria." (PMID 26088606, 2015). "There have been few cohort studies to longitudinally assess the association of TNF allele variants on malaria outcomes." (PMID 26088606, 2015). "So far, several studies show that severe malaria is associated with increased TNF-α, IFN-γ, and IL-1β but decreased IL-10 and TGF-β." (PMID 26602091, 2015). "The results reported here revealed that a combination of DDX39B, TNF and IL6 host genotypes were associated with manifestations of malaria, mainly by altering plasma levels of TNF and IL-6." (PMID 25038626, 2014). "Systemic symptoms of malaria like fever occur after the rupture of malaria schizont and are caused by the release of proinflammatory cytokine TNF-α." (PMID 24669217, 2014). "This indicates that protection against blood-stage malaria is associated with low production of IL-1β, TNFα, IL-6 and a high biphasic production IFNγ by the liver." (PMID 25408684, 2014). "Inhibitors of PGE2 synthesis such as Hz, acetaminophen, and salicylates are associated with high levels of TNF-α and increased malaria severity and mortality." (PMID 24669217, 2014). "CD4+ T cells have been demonstrated to be the major source of both interferon-γ (IFN-γ) and tumor necrosis factor alpha (TNF-α) during experimental malaria in mice which are implicated in both protection and pathology of this disease." (PMID 24904561, 2014). "High plasma levels of TNF are related to the pathogenesis of signs associated with malaria, such as fever, and severe forms of infection, such as cerebral malaria and severe anemia." (PMID 25038626, 2014). "Previous studies suggested that higher levels of TNF cytokine have been correlated with malaria severity and death, and several SNPs in the promoter region of the TNF gene have been associated with different outcomes and severity of a malaria infection." (PMID 25124540, 2014). "Collectively, our findings demonstrate that platelet phagocytosis is associated to thrombocytopenia and correlates with TNF-α, a cytokine normally attributed to severity in malaria." (PMID 23723981, 2013). "A ratio of IL-10:TNF of less than 1 correlated with severe malaria whereas a ratio of more than 1 was associated with uncomplicated malaria." (PMID 23874969, 2013). "Up-regulated TGF-β, IL-6, or TNF are associated with a higher frequency of malaria complications and an overall poor malaria prognosis." (PMID 24188121, 2013). "In our study, high cord levels of TNF-α were associated with decreased risk of severe malaria, although this association was only marginally significant." (PMID 24130857, 2013).
malaria (continued). "Meanwhile, high levels of the anti-inflammatory cytokine IL-10, or high IL-10/TNF-α ratios, reduce the risk of severe malarial anemia, despite being associated with reduced parasite clearance in children with uncomplicated malaria." (PMID 24130857, 2013). "It is unclear what the mechanism at the basis of malaria-related preterm delivery is, though fever, anaemia, and high levels of TNF alpha or interleukin 10 have been identified as important risk factors." (PMID 23350023, 2013). "For example, the inflammatory cytokines TNF-α and IFN-γ can mediate parasite inhibition and killing, but high levels of TNF-α have also been associated with severe malaria syndromes such as cerebral malaria." (PMID 24130857, 2013). "LTA and TNF have long attracted attention as candidate genes for susceptibility traits for malaria, and several of their polymorphisms have been found to be associated with severe malaria phenotypes." (PMID 24098393, 2013). "Firstly, an increase in HIV replication in blood mononuclear cells exposed to either malaria antigens or malaria pigment has been observed, and this was shown to be associated with increased production of TNF-α." (PMID 23327493, 2013). "The expressions of NF-κB p65 in the PBMCs from malaria patients and the plasma levels of IL-10 and TNF were measured by using enzyme-linked immunosorbent assay (ELISA)." (PMID 22682094, 2012). "High concentrations of TNF-α are related to the pathogenesis of symptoms associated with malaria, such as fever, and severe forms of infection, such as cerebral malaria." (PMID 23316245, 2012). "P. falciparum infection is associated with elevated levels of TNF and other monocyte-derived cytokines that cause fever and other symptoms of malaria." (PMID 22623996, 2012). "In the uncomplicated malaria group Δ22 homozygosity was associated with elevated IL-6 production (p = 0.04), and at least one long GTn allele was associated with elevated serum TNF (p = 0.007)." (PMID 22336003, 2012). "Excessive levels of these cytokines correlate with the development of severe malaria syndromes; for example, TNF causes dyserythropoiesis that contributes to the development of severe malarial anemia." (PMID 22623996, 2012). "The increasing serum TNF levels were reported to be associated with increased mortality in Malawian children with severe malaria." (PMID 22682094, 2012). "The main effects (i.e. without considering an interaction) of IFNγ-IL2+TNF−, IFNγ-IL2+TNF+, and IFNγ-IL2-TNF+ CD4+ T cells were reductions in the risk of clinical malaria of varying statistical significance." (PMID 23300801, 2012). "In uncomplicated malaria patients, Δ22 homozygosity was associated with elevated serum IL-6 (p = 0.04), and long GT repeat alleles were associated with elevated TNF (p = 0.007)." (PMID 22336003, 2012). "Studies in Gabon associated the TNF −308G>A polymorphism with a shorter interval to malaria reinfection and the TNF −238G>A polymorphism with protection against mild symptomatic malaria." (PMID 23316245, 2012). "In the uncomplicated malaria group, children with at least one long GTn repeat allele produced the most TNF (p = 0.007), and children homozygous for Δ22 produced the most IL-6 compared to children with other genotypes (p = 0.041)." (PMID 22336003, 2012). "When analyzing clinical_malaria versus asymptomatic infection group, associations were observed with the TNF-376 promoter SNP (rs1800750, OR:0.086, 95% CI: 0.016–0.473; P = 0.0026), previously associated in a number of other malaria studies." (PMID 22615793, 2012). "TNF1304 within intron 3 was associated with variation in mild malaria and parasitaemia, and TNF-308A and TNF-238A allele have been associated with high anti-P." (PMID 22947458, 2012). "On applying the fourth of the Prentice criteria, we found that vaccination group was still an independent predictor of clinical malaria risk in a multivariable model including CD4+ TNFα+ cells (HR = 0.69, 95%CI 0.48–0.97, p = 0.036)." (PMID 21998698, 2011).
malaria (continued). "Monocyte activation during P. falciparum infection is believed to produce elevated levels of TNF and other monokines implicated in the pathogenesis of malaria." (PMID 21532754, 2011). "A ratio of TNF∶IL-10 that favours TNF has been associated with severe malaria in children, and with LBW outcomes of PM." (PMID 21966395, 2011). "In a multivariable analysis TNFα+ CD4+ T cells were independently associated with a reduced risk for clinical malaria among RTS,S/AS01E vaccinees (HR = 0.64, 95%CI 0.49–0.86, p = 0.002)." (PMID 21998698, 2011). "TNF has been shown to be elevated in severe malaria, and TNF promoter region -238A allele together with -376A allele are associated with susceptibility to severe malaria." (PMID 20846452, 2010). "In this study, the (GT)n repeat polymorphism in the promoter region of the inducible HO-1 and six mutations of TNF from malaria patients (Thai, Burmese and Karen), in Mae Sot endemic area, were analysed." (PMID 20846452, 2010). "A recent genome wide association study found that only rs2516486 at TNF was weakly associated with malaria severity, however the authors caution that the candidate SNPs examined in this study were poorly tagged by the 500 K array used." (PMID 21029472, 2010). "Association analysis of SNPs across the LTA/TNF/LTB gene locus genotyped in severe malaria cases and controls." (PMID 21029472, 2010). "Various studies have investigated the relation existing between TNF promoter alleles and severity of malaria." (PMID 20846452, 2010). "TNF polymorphisms have been associated with malaria transmission and SM, primarily in populations originating and living in malaria endemic areas." (PMID 21029472, 2010). "Among low birth weight children, the TNF -308 A allele was also found to be associated with severe anaemia with a trend toward a risk for severe malaria anaemia." (PMID 20846452, 2010). "Our data on the associations of these clinical parameters with TNF-α essentially due to pregnancy associated malaria are thus in line with these previous observations." (PMID 19956547, 2009). "Our results indicated association of the -1031 and -863 TNF SNPs with increased risk of severe malaria." (PMID 18194515, 2008). "A recent study on Thailand/Myanmar border populations reported association of the TNF -1031C, -863C, -857C allele with severe malaria." (PMID 18194515, 2008). "Taken together, our data indicated a strong correlation between the TNF -1031 and -863 SNPs and cytokine levels in individuals, association of high TNF level with severe malaria as well as correlation of -1031C and -863A polymorphisms with disease severity." (PMID 18194515, 2008). "A recent study on lethal malaria in mice has implicated high levels of TNF in impairment of dendritic cell function thus contributing to immunosuppression associated with malaria." (PMID 18194515, 2008). "Severe malaria has been associated with high TNF-α plasma levels in conjunction with increased production of IFN-γ and IL-1β and decreased production of anti-inflammatory cytokines, notably IL-10 and TGF-β." (PMID 17997848, 2007). "The cross-linking of CD23 on macrophages or on other CD23-bearing effector cells by IgE-containing immune complexes is thought to play a pathogenic role in malaria via TNF-mediated pathways." (PMID 17204149, 2007). "The pro-inflammatory cytokines most closely investigated in malaria, such as TNF, usually act as homeostatic agents, but can cause pathology if produced excessively." (PMID 17029647, 2006). "Additionally, higher levels of IL-1β and tumor necrosis factor (TNF) -α have been linked to malaria severity, underscoring their importance in the inflammatory response." (PMID 41194029, 2025). "Both TNFα and C5a are implicated in severe malaria and placental malaria." (PMID 40624161, 2025).
malaria (continued). "Notably, elevated TNFα levels have been implicated in the severity of CM, with survivors exhibiting twofold higher plasma TNFα levels compared to uncomplicated malaria patients, and deceased cases showing 10‐fold increases." (PMID 40457525, 2025). "Elevated levels of TNF-α and IL-6 have been linked to severe malaria and poor clinical outcomes." (PMID 40061813, 2025). "TNF-α elevation has been previously associated with anemia and high-density P. falciparum infection, whereas reduced IL-10 demonstrated in African children with severe malaria-induced anemia." (PMID 40014608, 2025). "The dual role of TNF-α in malaria, both protective and pathogenic, poses challenges." (PMID 38694310, 2024). "Elevated levels of TNF-α, IL-1β, and IL-6 are commonly associated with severe malaria." (PMID 38694310, 2024). "It has been observed that TNF-α, IL-31, and IL-33 are associated with clinical or severe malaria." (PMID 39204168, 2024). "TNF is known for malaria killing, however, it also is associated with severe malaria development." (PMID 38099246, 2023). "However, TNF- α is the main cytokine that has been associated with the severe forms of malaria, cerebral malaria." (PMID 37215099, 2023). "Mohamedahmed and Abakar implicated high TNF-α plasma levels with susceptibility to severe malaria, and this was corroborated with previous reports that showed that TNF - 238G/A, a TNF-α SNP was associated with severe malaria and/or progression from uncomplicated malaria infection to severe malaria." (PMID 37215099, 2023). "TNF-α is an important human cytokine that is implicated in malaria pathogenicity." (PMID 37215099, 2023). "Furthermore, in both types of malaria (severe and uncomplicated), Gal-9 levels were associated with various pro- and anti-inflammatory cytokines and chemokines, including TNF, IL-6, IFN-α2, IFN-γ, IL-1Ra, and IL-10." (PMID 38067100, 2023). "Although the frequency of TNFα -308G >A in Asian populations such as Thailand, Myanmar, Sri Lanka, India, and Vietnam was found to be low (0.06–2.00%), the association between TNFα -308G >A polymorphism and malaria clinical outcomes remains evidently clear." (PMID 37910577, 2023). "Studies in Gabon found out that TNF −308G > A polymorphism has less space for recurrent malaria." (PMID 35291755, 2022). "TNF-α is the cytokine most implicated in the development of the clinical signs of malaria, while IL-10 and IL-6 are present at high levels in patients with symptomatic malaria." (PMID 35421083, 2022). "TNFα response capacity in malaria may be controlled by TNFα polymorphism, and our findings provide the rationale for conducting genetic analyses of the TNF gene locus in future IMRAS vaccine trials." (PMID 35062785, 2022). "The predominance of a pro-inflammatory cytokine profile in the absence of infection may be linked to the greater susceptibility of young children to severe malaria, which is determined by high IL-6 and TNF responses." (PMID 35421083, 2022). "TNFα is known to help control parasite expansion at early stages of infection but acting in a context-dependent manner to increase the risk of severe malaria during natural infection, with some reports suggesting that the TNFα response capacity in malaria is controlled by TNFα polymorphism." (PMID 35062785, 2022). "Malaria with severe manifestations may be caused by an elevated proinflammatory response (IL 6, IL 1, and tumor necrosis factor alpha increase during haemolysis from malarial infection)." (PMID 35897103, 2022). "Moreover, the pro-inflammatory cytokines such as TNF-α, and IL-6 have been associated with severe malaria and death." (PMID 36548650, 2022). "Additionally, in the high malaria transmission area (Obom), the mutant allele A of TNF-α 308 was found to significantly reduce the risk of asymptomatic infection compared to no infection in afebrile individuals." (PMID 35291755, 2022).
malaria (continued). "Plasmodium falciparum-infected individuals living in both high and low malaria transmission settings who carry the TNF-α 308 GA genotype are more likely to exhibit symptoms of malaria, whilst those with the B allele of the G6PD gene are likely to remain asymptomatic." (PMID 35291755, 2022). "However, the translational potential of TNFα and LTα for human CM is questionable, as, similar to IFNγ, TNFα and its receptors are associated with gaining immunity against malaria." (PMID 35514965, 2022). "Furthermore, high TNF-α/IL-10 ratio has also been associated with anaemia due to malaria in an earlier study." (PMID 34426742, 2021). "Inflammatory CD4+ T-cells that produce IFNγ and TNFα have been implicated in conferring protection from malaria in adults by preventing P. falciparum infection or its replication such that higher parasitemia and clinical malaria are diminished." (PMID 34414129, 2021). "However, excessive production of pro-inflammatory cytokines such IL-1β, IL-6 and TNF by monocytes/macrophages can result in systemic inflammation that causes fever and other disease manifestations of malaria." (PMID 33822828, 2021). "Moreover, tumour necrosis factor polymorphisms have been associated with severe malaria in African countries, most notably for this review, TNF-238 polymorphisms." (PMID 33985540, 2021). "The low levels of IFN-γ and TNF-α produced at this stage are associated with inhibition of parasite replication thereby reducing parasitaemia levels and this presents another layer of malaria disease prevention." (PMID 34666102, 2021). "A previous study suggests an important role for TNF-α as a risk factor for iNTS in malaria." (PMID 34177883, 2021). "In addition, there is a link between polymorphism within the TNF promoter region, parasitemia, and malaria severity." (PMID 34790829, 2021). "After we have analyzed the eight selected studies in this systematic review, we identified that the TNF-α level was found to be increased on the cerebral malaria group, suggesting TNF-α level could be closely linked to malaria." (PMID 32576141, 2020). "High TNF-α/IL-10 ratio has also been associated with anaemia due to malaria in an earlier study." (PMID 33195706, 2020). "In addition, others have reported moderate levels of TNF-α to be associated with parasite control by stimulating monocyte to phagocytose infected erythrocytes as well as activate calcium signaling in human malaria parasites." (PMID 33281757, 2020). "However, a low IL-10 to TNF-α ratio is associated with enhanced severity to malaria anemia and reduced serum IL-10 was observed in pediatric patients from Ghana with SMA." (PMID 32373101, 2020). "In genetically susceptible SLE individuals, malaria might be a trigger for increased production of TNF-α, besides other cytokines, triggering a cascade of events contributing to the development of SLE10,56–58." (PMID 31409832, 2019). "Furthermore, the role of promoter variants in clinical malaria (e.g., rs1800629) is highlighted by reports associating TNF with vulnerability to severe disease, including cerebral malaria and malaria in pregnancy." (PMID 31417551, 2019). "High levels of plasma TNF have also been associated with anemia and high-density P. falciparum infection in Zairian children, as well as being associated with other severe malaria complications such as renal failure." (PMID 30809232, 2019). "In malaria, a high level of TNF was associated with severe malaria, especially in children." (PMID 31871954, 2019). "TNF is a potent pro-inflammatory cytokine that has been implicated in malaria pathogenesis." (PMID 30809232, 2019). "In conclusion, TNF-α (G-238A & G-308A) variants are associated with higher plasma TNF-α levels in SLE patients residing in malaria endemic areas and could be a contributing factor in the development of SLE and susceptibility to severe P. falciparum malaria." (PMID 31409832, 2019).